MIOX (myo-inositol oxygenase)
Synonyms: ALDRL6
Tractability: Small molecule: a structure with a bound ligand is known.
Gene: Protein-coding gene on chromosome 22 (50,486,784 to 50,490,648, forward strand). Ensembl gene ENSG00000100253.
Subcellular location: Cytoplasm
Pathways (Reactome):
Metabolism: Synthesis of IP2, IP, and Ins in the cytosol
Gene Ontology:
Molecular function: ferric iron binding; inositol oxygenase activity; alcohol dehydrogenase (NADP+) activity; iron ion binding; oxidoreductase activity, acting on NAD(P)H
Biological process: inositol catabolic process
Cellular component: cytoplasm; cytosol; inclusion body
Genetic constraint (gnomAD): Loss-of-function variants: 51 observed, 43.4 expected, observed/expected ratio (o/e) 1.18, 90% interval 0.94 to 1.48. The upper end of that interval is the gene's LOEUF score, 1.48, which puts it in group 6 of 6, group 1 being the genes least tolerant of losing a copy. Missense variants: 395 observed, 385.34 expected, observed/expected ratio (o/e) 1.03, 90% interval 0.94 to 1.11. Synonymous variants: 168 observed, 156.22 expected, observed/expected ratio (o/e) 1.08, 90% interval 0.95 to 1.22.
Homologues: Orthologues: chimpanzee MIOX (99% identical), macaque MIOX (99% identical), guinea pig MIOX (90% identical), mouse Miox (90% identical), rat Miox (89% identical), pig MIOX (89% identical), dog MIOX (76% identical), tropical clawed frog miox (68% identical), zebrafish miox (67% identical), rabbit MIOX (57% identical), Drosophila melanogaster Miox (54% identical), Caenorhabditis elegans C54E4.5 (48% identical).
Diseases named in the same sentence as MIOX in open-access papers:
MIOX is named in the same sentence as 39 diseases in open-access papers, as found by Europe PMC text mining. Sharing a sentence is not in itself a finding about the gene and the disease. The quoted sentences say what the papers report.
acute kidney injury (9 papers, 2016 to 2024). Sudden and sustained deterioration of the kidney function characterized by decreased glomerular filtration rate, increased serum creatinine or oliguria. "In this investigation, a potentially novel signaling pathway in gentamicin-induced acute kidney injury—worsened by overexpression of proximal tubular enzyme, myo-inositol oxygenase (MIOX)—was elucidated." (PMID 35315361, 2022). "A previous study has demonstrated that overexpression of MIOX exacerbates cisplatin-induced acute kidney injury by regulating iron accumulation, GSH activity, and NADPH levels." (PMID 35338333, 2022). "The MIOX-KO mice may rescue the kidney from oxidant injury in ways similar to the iron sucrose (FeS), and protoporphyrin ameliorate prooxidant induced acute renal failure." (PMID 35315361, 2022). "MIOX is a renal tubular-specific novel marker for the early diagnosis of acute kidney injury." (PMID 29643901, 2018). "Overexpression of myo-inositol oxygenase (MIOX) exacerbates cellular redox injury in cisplatin-induced acute kidney injury (AKI) by accelerating ferroptosis." (PMID 34422642, 2021). "Previous studies found that overexpression of myo-inositol oxygenase (MIOX), a proximal tubular enzy me, can exacerbate kidney injury in cisplatin-induced acute kidney injury (AKI)." (PMID 38270638, 2024).
Hyperglycemia (7 papers, 2015 to 2025). An increased concentration of glucose in the blood. "In the state of hyperglycemia, abnormal expression of MIOX activates NLRP3 inflammasomes, leading to increased release of inflammatory mediators, promoting inflammatory response, leading to pancreatic cell damage, and exacerbating insulin resistance." (PMID 39966875, 2025). "MIOX is a 32-kDa cytoplasmic enzyme that is expressed in the proximal renal tubule and is upregulated in hyperglycemia." (PMID 35669435, 2022). "The observed increase in the myo-inositol concentration in the kidney extracts of db/db mice indicates tubular dysfunction and renal cell stress under hyperglycemia, likely due to the downregulated expression of the myo-inositol oxygenase in db/db mice." (PMID 26149603, 2015). "In diabetic complications, hyperglycemia is shown to accelerate MI catabolism via MIOX upregulation, resulting in toxic metabolite accumulation (e.g., xylitol) and exacerbation of retinal and neural tissue damage, thereby positioning MIOX as a potential therapeutic target for diabetic complications." (PMID 41020866, 2025). "Our previous studies indicated a potential role of MIOX, an enzyme highly expressed in renal proximal tubules, in the pathogenesis of tubular injury in states of hyperglycemia or diabetes, and accentuation of renal injury following high fat diet (HFD) administration." (PMID 32708636, 2020).
diabetes (6 papers, 2017 to 2025). "For instance, mulberry leaf extract upregulates MIOX expression and improves hepatic function, while cyclo (His-Pro) and canagliflozin suppress MIOX and improve diabetes and DN, respectively." (PMID 41020866, 2025). "MIOX, a tubular-specific enzyme, modulates redox imbalance and apoptosis in tubular cells in diabetes, resulting in tubulointerstitial fibrosis." (PMID 33081406, 2020). "In view of the role that MIOX plays in tissues, it can improve the oxidative stress, inflammatory reaction and ferroptosis of cells by regulating the expression level of MIOX, thus improving the blood sugar level of diabetes and the complications of diabetes." (PMID 39966875, 2025). "In addition, in diabetes, myo-inositol intracellular concentrations were reduced by the upregulation of the myo-inositol-degrading enzyme myo-inositol oxygenase (MIOX), a tubular-specific enzyme, and the glucuronate xylulose pathway was activated." (PMID 33081406, 2020). "Furthermore, MIOX overexpression has been already observed in other models of animal diabetes." (PMID 29053604, 2017). "Myo-inositol oxygenase (MIOX), which catabolizes myo-inositol to D-glucuronate, regulates apoptosis in tubular cells of diabetes." (PMID 34067150, 2021).
hepatocellular carcinoma (5 papers, 2023 to 2025). A malignant tumor that arises from hepatocytes. "It exacerbates ferroptosis in hepatocellular carcinoma by modulating the miR-362-3 p/MIOX axis, contributes to the ferroptosis-enriched microenvironment in glioma, and serves as a therapeutic target for ferroptosis induction in non-small-cell lung cancer." (PMID 41268533, 2025). "For instance, lncRNA NEAT1 promotes the expression of myo-inositol oxygenase (MIOX) by competitively binding to miR-362-3p, thus increasing the sensitivity of hepatocellular carcinoma cells to ferroptosis." (PMID 36765913, 2023). "For example, lncRNA-NEAT1 enhances MIOX expression by competitively binding to miR-362-3p, thereby increasing ferroptosis and offering a potential strategy for improving chemotherapy sensitivity in hepatocellular carcinoma (HCC) patients." (PMID 39544949, 2024). "In hepatocellular carcinoma (HCC), the long non-coding RNA NEAT1 has been reported to indirectly upregulate MIOX expression by modulating miR-362-3p, thereby promoting ferroptosis in HCC cells." (PMID 41020866, 2025). "LncNEAT1 competitively binds to miR-362-3p to increase the expression of myo-inositol oxygenase (MIOX), a non-heme-iron enzyme, to promote ROS production and the ferroptosis of hepatocellular carcinoma cells." (PMID 37686142, 2023).
diabetic kidney disease (4 papers, 2019 to 2025). Progressive kidney disorder caused by vascular damage to the glomerular capillaries, in patients with diabetes mellitus. "In diabetic nephropathy (DN) models, hyperglycemic conditions are reported to promote hypomethylation-dependent binding of the transcription factor Sp-1 to the MIOX promoter, resulting in upregulation of MIOX expression." (PMID 41020866, 2025).
Obesity (3 papers, 2020 to 2025). Accumulation of substantial excess body fat. "Furthermore, MIOX has been implicated in obesity and hypertension, with its upregulated expression observed in both spontaneous hypertensive and obesity models." (PMID 41020866, 2025). "In obesity-related MetS, MIOX expression is upregulated by fatty acids through the mTORC1/SREBP1 signaling axis, further perturbing renal tubular energy metabolism." (PMID 41020866, 2025). "Third-instar larvae of three independent D. melanogaster strains with reduced MIOX mRNA levels and reduced MIOX specific activity levels were shown to have a dramatic reduction in obesity and high-hemolymph glucose." (PMID 36835596, 2023). "Myo-inositol oxygenase (MIOX), a tubular enzyme, alters redox balance and subsequent tubular injury in the settings of obesity." (PMID 32708636, 2020). "Additionally, MIOX has been reported to disrupt cellular energy homeostasis by inhibiting the AMPK/sirtuins/PGC-1α/YY-1 pathway, thereby aggravating obesity-associated renal tubular injury." (PMID 41020866, 2025). "Besides altered redox balance, it is conceivable that MIOX upregulation may potentially perturb cellular energy sensors in the mitochondrial-rich proximal tubules, and thus may contribute towards renal injury in the settings of obesity." (PMID 32708636, 2020). "The foremost question that needed to be addressed was if obesity or HFD administration induces acute tubular damage, which would be correlative with the up- or down-regulation of MIOX." (PMID 32708636, 2020).
Insulin resistance (2 papers, 2025). Increased resistance towards insulin, that is, diminished effectiveness of insulin in reducing blood glucose levels. "In high-fat diet-fed murine models, insulin resistance and impaired metabolic health have been observed, accompanied by enhanced MIOX-mediated MI degradation in renal tissues." (PMID 41020866, 2025). "In patients with gestational diabetes mellitus, MI metabolic disorders were shown to be potentially exacerbated by aberrant elevation of MIOX activity, resulting in MI depletion and attenuation of insulin signaling, thereby promoting insulin resistance development." (PMID 41020866, 2025).
liver cancer (2 papers, 2023 to 2025). An epithelial or non-epithelial malignant neoplasm that arises from the liver. "miR-362-3p can promote the expression of MIOX and increase ferroptosis to alleviate the progression of liver cancer." (PMID 37008632, 2023). "A potential mechanism by which NEAT1 regulates tumors is that it indirectly increases the expression of inositol oxygenase (MIOX) by regulating miR-362-3p, thereby increasing the sensitivity of liver cancer cells to ferroptosis." (PMID 40959280, 2025).
colorectal cancer (1 paper, 2025). A primary or metastatic malignant neoplasm that affects the colon or rectum. "Conversely, in colorectal cancer (CRC), MIOX, as a methylation driver gene, is significantly upregulated in tumor tissues and observed to increase with disease progression." (PMID 41020866, 2025).
kidney damage (1 paper, 2023). "Still, the biological implications of the reduced detection of Myo-inositol oxygenase are not evident because kidney damage is a frequent clinical sign in CanL dogs." (PMID 36982564, 2023).
kidney injury (1 paper, 2025). Trauma to the kidney. "Furthermore, MIOX has been implicated in the pathogenesis of various disorders, including acute kidney injury, cancer, neurological diseases, as well as reproductive and developmental disorders." (PMID 41020866, 2025). "Its involvement in mediating oxidative stress, metabolic dysregulation, and cellular injury mechanisms has positioned MIOX as a promising candidate for both biomarker development and therapeutic targeting in kidney injury." (PMID 41020866, 2025).
lung squamous cell carcinoma (1 paper, 2025). "In patients with lung squamous cell carcinoma, elevated MIOX expression has been correlated with improved prognosis." (PMID 41020866, 2025).
metabolic syndrome (1 paper, 2025). A cluster of metabolic risk factors for CARDIOVASCULAR DISEASES and TYPE 2 DIABETES MELLITUS. "Dysregulation of MIOX activity disrupts MI metabolic balance, leading to pathological processes including oxidative stress, inflammation, and ferroptosis, which subsequently induce multiple diseases such as metabolic syndrome, neurological disorders, tumors, and reproductive/developmental disorders." (PMID 41020866, 2025).
renal carcinoma (1 paper, 2025). A carcinoma arising from the epithelium of the renal parenchyma or the renal pelvis. "In summary, proximal tubules are generally considered the origin of renal cancer, and the specifically expressed myo-inositol oxygenase (MIOX) gene may play a crucial role in the mechanisms underlying the occurrence and progression of RCC." (PMID 40341358, 2025). "However, whether overexpression of MIOX can exacerbate renal cancer cell death remains a mystery." (PMID 40341358, 2025).
renal cell carcinoma (1 paper, 2025). "In this study, we employed single-cell sequencing and spatial transcriptomics to characterize exosome-related genes in renal cell carcinoma, thereby gaining deeper insights into the potential role of MIOX in RCC development." (PMID 40341358, 2025).
staphylococcus aureus infection (1 paper, 2025). An infectious process in which the bacteria Staphylococcus aureus is present. "On the other hands, the pathway of Staphylococcus Aureus infection highly enriched in CD82 and MIOX, the pathway of proteasome highly enriched in CDKN1A and MYCN." (PMID 39966875, 2025).
tumor (5 papers, 2021 to 2025). "Additionally, MIOX was significantly involved in the abnormal immune infiltration of the tumor microenvironment and associated with the DNA damage repair process of PRAD." (PMID 35669435, 2022). "Since lower expression of MIOX is correlated with higher mortality, in this study, we demonstrated that high MIOX expression suppress tumor progression though inducing ferroptosis." (PMID 40341358, 2025). "Validation experiments through knockdown and overexpression in vitro and in vivo revealed that MIOX functions as a suppressor of tumor progression in RCC." (PMID 40341358, 2025). "This indicates that MIOX, as a key gene, is involved in the regulation of the cell cycle and metabolic pathways of tumor cells in PRAD." (PMID 35669435, 2022). "The results showed that AGL, SLC16A3, and MIOX were significantly high expressed in tumor samples, whereas HKDC1 and ALDH7A1 were significantly low expressed in tumor samples." (PMID 33991070, 2021). "Notably, in ccRCC, MIOX has been characterized as a pivotal regulatory molecule that suppresses tumor progression through the autophagy-ROS-STAT3/c-Myc signaling cascade." (PMID 41020866, 2025). "As depicted, lower MIOX expression was not prominently existed within the core region of tumor (identified by KRT7) but in tumor-adjacent tissue." (PMID 40341358, 2025). "On the contrary, RBP4 and MIOX were highly expressed in tumour cells 1 from ccRCC2, and ANXA1 and MUC20-OT1 were highly expressed in tumour cells 2 from ccRCC2 but lowly expressed in tumour cells 2 from ccRCC1." (PMID 34168986, 2021).
cancer (3 papers, 2019 to 2025). A tumor composed of atypical neoplastic, often pleomorphic cells that invade other tissues. "The expression level of MIOX has been closely associated with disease progression and prognosis in various cancers, demonstrating complex and diverse roles across different cancer types." (PMID 41020866, 2025).
metabolic disorders (3 papers, 2022 to 2025). "Metabolic dysregulation is recognized as a critical risk factor for multiple pathologies, in which abnormal expression of MIOX has been implicated in the pathogenesis and exacerbation of metabolic disorders through diverse mechanisms." (PMID 41020866, 2025). "Experimental evidence has positioned MIOX as a key regulatory molecule for renal tubular injury in metabolic diseases, with its expression and activity being regulated by fatty acids, insulin, and the mTORC1/SREBP1 pathway." (PMID 41020866, 2025). "MIOX is recognized as a key hub in the systemic regulation of metabolic disorders through its integration of energy metabolism and redox signaling." (PMID 41020866, 2025). "By comparing the p-value and hazard ratio, we analyzed the impact of each key gene on the survival of PRAD patients, and we selected MIOX as a hub gene regulating PRAD metabolic disorders (p = 0.019, HR = 1.193)." (PMID 35669435, 2022). "The central role of MIOX in metabolic diseases is characterized by its involvement in IR, oxidative stress, inflammatory cascades, and ferroptosis, thereby providing a molecular rationale for novel therapeutic strategies targeting MIOX." (PMID 41020866, 2025). "Although the precise mechanistic role of MIOX in PKD has not been thoroughly investigated, it can be speculated that the dysregulation of MIOX expression may exacerbate disease progression through oxidative stress and metabolic disorders based on corroborative evidence from other studies." (PMID 41020866, 2025). "Due to the upregulation of MIOX in T2DM, oxidative stress and endoplasmic reticulum stress are exacerbated, leading to mitochondrial energy metabolism disorders and exacerbating pancreatic islet beta cells damage." (PMID 39966875, 2025). "In metabolic disorders, the role of MIOX is not confined to DN but is extended to other metabolism-related pathologies." (PMID 41020866, 2025).
infection (2 papers, 2018 to 2023). The state of being infected such as from the introduction of a foreign agent such as serum, vaccine, antigenic substance or organism. "Herein, we attempted to determine whether myo‐inositol oxygenase (MIOX) has proinflammation enzyme in infection‐induced cardiac dysfunction (IICD) and its underlying mechanism." (PMID 37249295, 2023). "In this study, we only analyzed the expression of MIOX in patients with infection‐induced cardiac dysfunction and normal volunteer." (PMID 37249295, 2023). "Next, in infection‐induced mice with cardiac dysfunction, MIOX protein and mRNA expressions in heart tissue were induced." (PMID 37249295, 2023). "Trehalose-6-phosphate phosphatase and myo-inositol oxygenase were upregulated in young leaves after artificial infection while aldo/keto reductase and 1,3–beta glucan synthase were induced in mature leaves." (PMID 29541089, 2018). "We examined that the function of MIOX in an infection‐induced mice model of cardiac dysfunction." (PMID 37249295, 2023).
renal disease (2 papers, 2019 to 2025). "Among these discoveries, MIOX has been identified as a pivotal enzyme with critical roles in renal disease pathogenesis." (PMID 41020866, 2025).
kidney (1 paper, 2022). "In the kidneys of diabetic mice, the proximal tubular cells showed DNA hypomethylation of myo-inositol oxygenase (MIOX), which could be firmly bound by the transcription factor Sp1 on the gene promoter, thus mediating kidney damage progress." (PMID 35130617, 2022).
MIOX also shares sentences with these, for which no sentence is quoted: chronic kidney disease (2 papers); Nematode Infection (2); bladder cancer (1); clear-cell renal cell carcinoma (1); coronary heart disease (1); cyst (1); fibrosis (1); gastric adenocarcinoma (1); gestational diabetes mellitus (1); glioma (1); Hypertension (1); neurological diseases (1); non-small cell lung carcinoma (1); prostate adenocarcinoma (1); prostate carcinoma (1); type 2 diabetes mellitus (1); type 2 diabetic nephropathy (1).